LINC00484 (long independently transcribed non-coding RNA 484)
Synonyms: C9orf73
Gene: Long non-coding RNA gene on chromosome 9 (91,118,361 to 91,183,601, forward strand). Ensembl gene ENSG00000235641.
Diseases named in the same sentence as LINC00484 in open-access papers:
LINC00484 is named in the same sentence as 1 disease in open-access papers, as found by Europe PMC text mining. Sharing a sentence is not in itself a finding about the gene and the disease. The quoted sentences say what the papers report.
Nephroblastoma (1 paper, 2020). An embryonal neoplasm characterized by the presence of epithelial, mesenchymal, and blastema components. "Using MCODE in Cytoscape, 4 key genes (PVT1, hsa-mir-187, hsa-mir-551a, and LINC00484), which may play an important role in the development of nephroblastoma, were found to be densely connected." (PMID 32149111, 2020).